RN7SL332P (RNA, 7SL, cytoplasmic 332, pseudogene)
Gene: Miscellaneous RNA gene on chromosome 6 (15,112,968 to 15,113,221, forward strand). Ensembl gene ENSG00000242989.
Homologues: Orthologues: chimpanzee Metazoa_SRP (99% identical), macaque Metazoa_SRP (94% identical). Paralogues in human: RN7SL2 (85% identical), RN7SL1 (85% identical), RN7SL3 (84% identical), RN7SL664P (83% identical), RN7SL45P (82% identical), RN7SL47P (82% identical), RN7SL630P (82% identical), RN7SL712P (82% identical), RN7SL126P (81% identical), RN7SL166P (81% identical), RN7SL444P (81% identical), RN7SL147P (81% identical), and 706 more.